MTPAP (mitochondrial poly(A) polymerase)
Description:
Polymerase that creates the 3' poly(A) tail of mitochondrial transcripts. Can use all four nucleotides, but has higher activity with ATP and UTP (in vitro). Plays a role in replication-dependent histone mRNA degradation. May be involved in the terminal uridylation of mature histone mRNAs before their degradation is initiated. Might be responsible for the creation of some UAA stop codons which are not encoded in mtDNA.
Synonyms: PAPD1; FLJ10486; SPAX4; TENT6
Tractability: Small molecule: it has a binding pocket of medium quality. PROTAC: ubiquitination databases record sites on it; its protein half-life has been measured.
Gene: Protein-coding gene on chromosome 10 (30,309,801 to 30,374,448, reverse strand). Ensembl gene ENSG00000107951.
Subcellular location: Cytoplasm; Mitochondrion
Subcellular location (Human Protein Atlas): Mitochondria; Nucleoplasm; Vesicles
Pathways (Reactome):
Metabolism of RNA: Mitochondrial mRNA modification
Gene Ontology:
Molecular function: ATP binding; identical protein binding; magnesium ion binding; manganese ion binding; poly(A) RNA polymerase activity; protein binding; protein homodimerization activity; RNA binding; UTP binding
Biological process: histone mRNA catabolic process; mitochondrial mRNA polyadenylation; mitochondrial RNA 3'-end processing; mRNA 3'-end processing; RNA 3'-end processing
Cellular component: cytoplasm; mitochondrion; mitochondrial matrix
Genetic constraint (gnomAD): Loss-of-function variants: 23 observed, 50.84 expected, observed/expected ratio (o/e) 0.45, 90% interval 0.32 to 0.64. The upper end of that interval is the gene's LOEUF score, 0.64, which puts it in group 2 of 6, group 1 being the genes least tolerant of losing a copy. Missense variants: 614 observed, 728.41 expected, observed/expected ratio (o/e) 0.84, 90% interval 0.79 to 0.9. Synonymous variants: 257 observed, 268.96 expected, observed/expected ratio (o/e) 0.96, 90% interval 0.86 to 1.06.
Gene-disease validity (ClinGen):
ClinGen rates the evidence that MTPAP causes each of these diseases.
mitochondrial disease (autosomal recessive): Definitive.
Homologues: Orthologues: chimpanzee MTPAP (99% identical), macaque MTPAP (89% identical), dog MTPAP (81% identical), pig MTPAP (80% identical), rat Mtpap (77% identical), mouse Mtpap (76% identical), rabbit MTPAP (76% identical), guinea pig MTPAP (75% identical), zebrafish mtpap (53% identical), tropical clawed frog mtpap (52% identical), Drosophila melanogaster MTPAP (27% identical), Caenorhabditis elegans cid-1 (16% identical), and 6 more. Paralogues in human: TUT1 (26% identical), TUT7 (19% identical), TUT4 (18% identical), TENT2 (15% identical).
Diseases named in the same sentence as MTPAP in open-access papers:
MTPAP is named in the same sentence as 17 diseases in open-access papers, as found by Europe PMC text mining. Sharing a sentence is not in itself a finding about the gene and the disease. The quoted sentences say what the papers report.
spastic ataxia (7 papers, 2014 to 2024). "Severe reduction of poly(A) tails has been reported in patients with spastic ataxia with optic atrophy due to mutations in mtPAP, resulting in both increased and decreased mRNA steady-state levels." (PMID 26152302, 2015). "The p.N478D missense mutation in human mitochondrial poly(A) polymerase (mtPAP) has previously been implicated in a form of spastic ataxia with optic atrophy." (PMID 25008111, 2014). "In this study, there was no causative mutation associated with spastic ataxia, such as SACS/VAMP1/KIF1C/MARS2/MTPAP/AFG3L2(AR), detected." (PMID 35572931, 2022).
optic atrophy (5 papers, 2014 to 2024). A disorder characterized by loss of optic nerve fibers. "The homozygous p.N478D missense mutation in MTPAP causes spastic ataxia autosomal recessive Type 4 (SPAX4), a severe progressive neurodegenerative human disorder characterized by profound muscle-tone abnormalities and optic atrophy." (PMID 26319014, 2015).
colon cancer (1 paper, 2020). "NUDT21, CPSF3, CSTF2, and MTPAP were overexpressed while PCF11 and PABPN1 were suppressed in colon cancer tissues." (PMID 32153636, 2020).
epilepsy (1 paper, 2025). A brain disorder characterized by episodes of abnormally increased neuronal discharge resulting in transient episodes of sensory or motor neurological dysfunction, or psychic dysfunction. "In contrast, some genes (RPL4, MTPAP, and SNX30) that are downregulated in the PZ also showed downregulation in epilepsy samples in the TLE versus healthy scRNA dataset." (PMID 39541170, 2025).
uterine cancer (1 paper, 2025). Primary or metastatic malignant neoplasm involving the uterine corpus and/or the cervix.
peripheral neuropathy (1 paper, 2022). A disorder affecting the peripheral nervous system. "In four patients, we identified four disease-causing genes, of which variants in PDHB, MTPAP, and SUCLA2 have been reported not as a cause of CMT but of other diseases associated with symptomatic or subclinical peripheral neuropathy." (PMID 35235001, 2022).
MTPAP also shares sentences with these, for which no sentence is quoted: Ataxia (2 papers); autosomal recessive spastic ataxia (1); Autosomal recessive spastic ataxia of Charlevoix-Saguenay (1); cancer (1); Depression (1); Hypoglycemia (1); neurodegenerative disease (1); periodontitis (1); retinitis pigmentosa (1); spastic ataxia type 4 (1); tumor (1).